PTH (parathyroid hormone)
Diseases named in the same sentence as PTH in open-access papers (continued):
Sharing a sentence is not in itself a finding about the gene and the disease.
Hypercalcemia (continued). "In patients with PTH-independent hypercalcaemia, the measurement of vitamin D metabolites using LC–MS/MS analytical technique, followed by genetic testing (e.g., NGS technique), may help to identify carriers of CYP24A1 mutations." (PMID 38665259, 2024). "The hypophosphatasia/hyperphosphatasia misdiagnosis (i.e., June 2023) can be easily rejected since the blood count and urine test displayed no such signs (i.e., high phosphate serum levels, low levels of parathyroid hormone due to hypercalcemia and hypercalciuria)." (PMID 39201019, 2024). "Meta-analyses show similar PTH reductions to paricalcitol with fewer hypercalcaemia events." (PMID 39208984, 2024). "She had parathyroid hormone (PTH)-independent hypercalcemia, which could be due to malignancy, bone metastasis, or thyrotoxicosis." (PMID 39703928, 2024). "The first case reports of HCINF1 were published in the 1950s, when approximately 200 cases of PTH-independent hypercalcaemia in infants were noted in the United Kingdom because of the wide use of formula milk enriched with increased doses of vitamin D (up to 4000 International Units (IU))." (PMID 38665259, 2024). "In patients with secondary HPT and normal serum calcium at transplantation, PTH normalized in roughly one third of patients after transplantation, about 50% remained elevated but with normal serum calcium levels, and around 15% developed de novo hypercalcemia." (PMID 39001249, 2024). "Considering the most common cause of hypercalcemia, which is primary hyperparathyroidism (PHPT), the first step in the diagnostic process should be excluding this condition, by measuring the amount of PTH." (PMID 38920679, 2024). "Parathyroid carcinoma should be highly suspected when extremely high levels of PTH and severe hypercalcemia are present, which cannot be simply explained by a preoperatively localized parathyroid adenoma, especially when suspicious malignant adhesion is found during intraoperative exploration." (PMID 39054438, 2024). "Furthermore, CaSR is intricately involved in the intracellular degradation of PTH during episodes of hypercalcemia." (PMID 38920679, 2024). "Based on these findings, one may hypothesize that both high PTH levels and hypercalcemia could contribute to the development of cardiometabolic disorders in PHPT." (PMID 39404961, 2024). "Histoplasmosis is an infrequent etiology of PTH-independent hypercalcemia." (PMID 39439809, 2024). "The KDOQI guideline for CKD-MBD in 2003 defines severe hyperparathyroidism as persistently elevated serum intact-PTH levels exceeding 800 pg/mL (88 pmol/L), accompanied by hypercalcaemia or hyperphosphataemia, and exhibiting poor responsiveness to medical interventions." (PMID 39208984, 2024). "In our experience, severe hypercalcemia with a PTH value of more than 10–15 times the upper limit coexisted in two patients, whereas the other two were not biochemically suggestive of carcinoma (calcium <14 mg/dL), even though their PTH levels were extremely high." (PMID 39768933, 2024). "Assessment of first-degree relatives revealed the presence of hyperparathyroidism (hypercalcemia and hypercalciuria with high levels of PTH) in the proband’s brother (individual II-1) and daughter (individual III-1), and both were also heterozygous for the D418N mutation and developed melanomas." (PMID 38891107, 2024). "The development of hypercalcemia is intensified by elevated calcitriol levels due to increased 1-alpha-hydroxylase and decreased 24-hydroxylase activity, both triggered by heightened PTH stimulation in the kidneys." (PMID 39519190, 2024). "Familial hypocalciuric hypercalcemia type I (FHH1) is caused by heterozygous loss-of-function mutations in the CaSR gene, and is characterized by the combination of hypercalcemia, hypocalciuria, normal to elevated PTH, and facultatively hypermagnesemia and mild bone mineralization defects." (PMID 38386045, 2024).
Hypercalcemia (continued). "In many cases, the originating primary parathyroid NET might not be obvious at first presentation for pancreatitis, meaning that PTH-derivate hypercalcemia may act completely asymptomatic (or unrecognized) until the episode of pancreatic involvement." (PMID 38928056, 2024). "PTH during the first admission was inappropriately normal for the degree of hypercalcemia." (PMID 39350812, 2024). "FHH is often diagnosed in asymptomatic hypercalcemic patients with a family history of hypercalcemia, normal serum PTH levels, and very low urinary calcium excretion (<100 mg/24 hours), with a calcium-to-creatinine clearance ratio (Ca/Cr) typically less than 0.01." (PMID 39246902, 2024). "Other data suggest that calcium supplements may induce transient hypercalcemia and reduce parathyroid hormone (PTH) levels, which could potentially contribute to lowered blood pressure." (PMID 38345765, 2024). "Hypercalcemia and elevated PTH levels were observed in two (1.0%) patients." (PMID 39104811, 2024). "Although malignancy is the most common cause of hypercalcaemia with suppressed PTH, a malignancy workup is not always necessary if an alternative diagnosis is strongly supported." (PMID 39434928, 2024). "Excessive vitamin D or calcitriol ingestion, ectopic production of 1,25(OH)2D3 in granulomatous or lymphoproliferative disease and genetically determined dysregulation of vitamin D metabolism may lead to PTH-independent hypercalcaemia." (PMID 38665259, 2024). "The resultant suppression of PTH occurs independently of changes in systemic 1,25D levels and without causing hypercalcemia." (PMID 39688907, 2024). "We hypothesized that hypotension in this patient resulted from a transient increase in PTH release due to stimulation during intubation compounded by chronic hypercalcemia-induced dehydration." (PMID 39213244, 2024). "In opposition native vitamin D is unlikely to cause hypercalcemia, as 1-hydroxylase activation is regulated by PTH, FGF-23, 24–hydroxylase." (PMID 38397979, 2024). "Elevated PTH may indicate a parathyroid adenoma, whereas low PTH is more suggestive of malignancy-related hypercalcemia." (PMID 39539908, 2024). "However, in our case, the isolated PHPT was incidentally diagnosed in an asymptomatic child on the basis of laboratory abnormalities (hypercalcemia, elevated PTH, and hypophosphatemia)." (PMID 39444450, 2024). "Higher dialysate Ca2+ levels (1.75 mmol/L) may help manage low PTH and prevent hypercalcemia but may exacerbate vascular calcification and stiffness, contributing to cardiovascular complications." (PMID 39457714, 2024). "Excluding primary hyperparathyroidism, tumor, vitamin D intoxication and low alkaline phosphatase, unexplained hypercalcemia, combined with the increase of urinary calcium excretion and suppressed parathyroid hormone (PTH), were previously named idiopathic infantile hypercalcemia (IIH)." (PMID 38504242, 2024). "Due to the relatively short follow-up period and the fact that both serum PTH and calcium values were within the normal range in this cohort, it is uncertain whether the decline in PTH is a precursor to the occurrence of hypercalcemia." (PMID 38181430, 2024). "Idiopathic infantile hypercalcemia (IIH) is a rare disorder of PTH-independent hypercalcemia." (PMID 38504242, 2024). "Suppressed PTH and elevated bone turnover markers and urine calcium excretion are early markers of the rebound phenomenon that precede hypercalcemia and may assist in identifying impending hypercalcemia." (PMID 38041865, 2024). "Excessive secretion of PTH results in persistent hypercalcemia and hypophosphatemia." (PMID 39834923, 2024). "This non-PTH-dependent hypercalcemia resolved after re-initiation of denosumab." (PMID 39529981, 2024).
Hypercalcemia (continued). "This case had similar findings to other reports in the literature detailing silicone-induced hypercalcemia, which also reported abnormal imaging or nephrolithiasis, low-normal parathyroid hormone (PTH), normal 25-hydroxyvitamin D, and elevated 1,25-dihydroxyvitamin D." (PMID 39350812, 2024). "The hypoactivity of calcium-sensing receptor (CaSR) facilitates calcium (Ca2+) renal absorption and parathormone (PTH) production despite mildly elevated serum Ca2+ levels, resulting in different degrees of hypercalcemia, hypocalciuria and inappropriately elevated PTH." (PMID 38214877, 2024). "Hypercalcemia, PTH level was elevated and the thyroid function was normal." (PMID 39712793, 2024). "Laboratory tests revealed hypokalemia due to renal potassium wasting, hypomagnesemia, metabolic alkalosis, hypocalciuria, hypercalcemia, elevated PTH level, hyperreninemia, and normal bone mineral density assessed via dual-energy X-ray absorptiometry of the hip joint and lumbar spine." (PMID 39183425, 2024). "Clinical features of parathyroid carcinomas are like parathyroid adenoma; however, patients with parathyroid carcinomas are more likely to have symptoms, a neck mass, bone and kidney disease, marked hypercalcemia, and very high serum parathyroid hormone concentrations." (PMID 39822449, 2024). "Activating parathyroid hormone (PTH)/PTH‐related Peptide (PTHrP) receptor (PTH1R) mutations causes Jansen's metaphyseal chondrodysplasia (JMC), a rare disease characterized by growth plate abnormalities, short stature, and PTH‐independent hypercalcemia." (PMID 37808400, 2023). "Lab tests showed hypercalcemia (2.97 mmol/L) and elevated PTH (2423 pmol/L)." (PMID 36334246, 2023). "These patients’ charts were re-examined six months later and a determination of whether a PTH level was performed as well as any referrals explicitly for hypercalcemia or PHPT was done." (PMID 36843806, 2023). "The high prevalence of AH among patients with PHPT may be due to both the direct effect of hypercalcemia and the direct effects of PTH on cardiomyocytes, however, this requires further study in basic research." (PMID 37465121, 2023). "PTH subsequently became undetectable, however hypercalcemia and hypercalciuria persisted." (PMID 37701149, 2023). "Laboratory investigations in our hospital showed hypercalcemia and elevated PTH level." (PMID 37415163, 2023). "Thus, kidney-specific SIK deletion in mice resulted in Cyp27b1 stimulation, which led to PTH-independent, 1,25-vitamin D–dependent hypercalcemia." (PMID 36862513, 2023). "When hypercalcemia was found, PTH may be needed and BT should be excluded to make the diagnosis accurate." (PMID 36820584, 2023). "Furthermore, several case reports suggest that cinacalcet can be used in PTH-independent hypercalcemia that is refractory to antiresorptive therapy." (PMID 37328745, 2023). "A review of the clinical, laboratory, imaging, and pathologic findings in our patients with the GCM2 p.Tyr394Ser variant showed that all patients had asymptomatic disease and mild (patients 1 and 3) or moderate (patient 2) hypercalcemia, with mild to moderate elevated PTH." (PMID 38130397, 2023). "PTHrP is less likely than PTH to stimulate the production of 1,25-dihydroxyvitamin D, so the measurement of 1,25-dihydroxyvitamin D in patients with PTHrP-mediated hypercalcemia may be variable." (PMID 37033238, 2023). "Remarkably, as reported for his sister, patient 2, this patient presented a decrease in the occurrence of hypo- and hypercalcemia, and a significant decrease in PTH requirements from 42.4 ± 0.7 μg/day to 21.2 ± 0.7 μg/day (p < 0.0001) suggesting a partial remission of hypoparathyroidism." (PMID 38112858, 2023). "First, NVD is unlikely to cause hypercalcemia unless high doses are consistently given because its 1α-hydroxylase-mediated activation process is regulated by many factors, such as PTH, FGF23, and 24-hydroxylase." (PMID 37904427, 2023).
Hypercalcemia (continued). "Initial laboratory studies revealed hypercalcemia and elevated parathyroid hormone levels." (PMID 37753019, 2023). "However, parathyroid hormone-independent hypercalcemia and hypophosphatemia are observed, suggesting a need for close monitoring and timely intervention during human testing." (PMID 37311769, 2023). "Despite standard care (intravenous fluids, furosemide, and calcitonin), the hypercalcemia rose to 16.5 mg/dL; pamidronate administration induced a drop to 14 mg/dL, which was followed by emergency parathyroidectomy that achieved control of the PTH excess." (PMID 37893182, 2023). "Additionally, at single case report level, we mention a 35-year-old woman who experienced a markedly elevated hypercalcemia (of 21 mg/dL) with suppressed PTH while being pregnant (32 weeks of gestation)." (PMID 37296804, 2023). "Analysis of the largest group of long-term survivors reported to date demonstrated only very modest growth of the xenograft, inefficient participation of the porcine organ in the recipient RAAS pathway, and a remarkably reproducible PTH-independent hypercalcemia and hypophosphatemia." (PMID 37311769, 2023). "Specifically, 13 patients with PC and 5 with AA showing marked hypercalcemia and/or considerably elevated PTH levels, as well as 5 patients with PC and 2 with AA displaying intra-operative signs of macroscopic infiltration or adherence to adjacent structures, underwent a more extensive neck surgery." (PMID 37223026, 2023). "However, animal studies show that calcimimetics can reduce the hypercalcemia induced by teriparatide, suggesting a role for calcimimetics in the treatment of PTH-independent hypercalcemia." (PMID 37328745, 2023). "The authors postulated that hypercalcemia may have occurred due to inhibition of CYP enzymes responsible for the metabolism of vitamin A or via PTH-mediated hypercalcemia." (PMID 37274338, 2023). "Excess intake of dietary vitamin D can cause hypercalcemia, hyperphosphatemia, and suppression of PTH, none of which were observed in this study." (PMID 37621865, 2023). "Furthermore, case 2 had a different presentation with bone pain and hypercalcemia before the appearance of subcutaneous nodules, with normal PTH over the past 3 years." (PMID 37264371, 2023). "Primary hyperparathyroidism most commonly presents as an asymptomatic condition with mild hypercalcemia on biochemical screening On rare occasion, however, patients can present with dramatic symptoms related to sudden, severe hypercalcemia due to a rapid rise in parathyroid hormone (PTH)." (PMID 36627692, 2023). "This is associated with a decrease in serum parathyroid hormone (PTH) and, finally, a loss of calcium homeostasis with severe manifestations such as anorexia, nausea, vomiting, diarrhea, hypercalcemia and hypercalciuria, nephrocalcinosis, cardiocalcinosis, and soft tissue calcification." (PMID 35162272, 2022). "Compared with matched controls without hypercalcemia, high-risk patients with hypercalcemia and PTH greater than or equal to 50 pg/mL experienced significantly increased rates of all symptoms and diagnoses associated with PHP." (PMID 36574247, 2022). "Lack of determination of VDBP, free 25-OH vit D, free and total 1.25 di hydroxy vit D, vitamin D metabolites, and parathyroid hormone concentration could have provided further mechanistic insight for the etiology of hypercalcemia." (PMID 35458212, 2022). "Patients with established metastasis have profound hypercalcemia due to high PTH levels." (PMID 36532647, 2022). "Hypercalcemia may be divided into: Hypercalcemia with increased PTH (i.e. PTH above normal range) and hypercalcemia with decreased PTH (i.e. PTH below normal range)." (PMID 36547749, 2022). "The parathyroid hormone (PTH)–related protein (PTHrP) is indispensable for the development of mammary glands, placental calcium ion transport, tooth eruption, bone formation and bone remodeling, and causes hypercalcemia in patients with malignancy." (PMID 35933010, 2022).
Hypercalcemia (continued). "Hypercalcemia with increased PTH stems from primary or tertiary hyperparathyroidism." (PMID 36547749, 2022). "Most parathyroid cancers release PTH and consequently induce hypercalcemia." (PMID 36532647, 2022). "After admission, the biochemical assays revealed hypercalcaemia (2.76 mmol/L), hypophosphatemia (0.70 mmol/L), elevated PTH levels (134.60 pg/mL), reduced 25-hydroxyvitamin D3 levels (15.2 ng/mL; normal range 20–32) and normal levels of 24-hour urinary calcium (3.64 mmol/24 h)." (PMID 35945539, 2022). "Therefore, pHPT is defined biochemically by hypercalcemia and elevated or inappropriately normal levels of PTH." (PMID 34991581, 2022). "The FDA approval for recombinant salmon calcitonin for treating hypercalcemia and postmenopausal osteoporosis in 2005 and the parathyroid hormone (PTH) for osteoporosis in 2002 are two success stories of the recombinant technology in the production of peptide therapeutics." (PMID 35203552, 2022). "Hypercalcemia with elevated parathyroid hormone level suggested a parathyroid adenoma." (PMID 35296318, 2022). "We propose that the calcium-reducing effects of statins may not solely be limited to lithium users and may be beneficial to other forms of hyperparathyroidism and PTH-dependent hypercalcemia." (PMID 36153583, 2022). "However, although the treatment has been shown to be beneficial in terms of reducing PTH levels by 40 to 60% in different randomized control trials, development of hypercalcemia is a possible adverse effect that needs to be closely monitored." (PMID 36501215, 2022). "When hypercalcemia is independent of PTH, primary (genetic) and secondary causes such as malignancy should be studied." (PMID 36518777, 2022). "Real-world clinical effectiveness and safety varied across the therapies under investigation, but only ERC effectively raised mean 25D (to well above 30 ng/mL) and reduced mean PTH levels without causing hypercalcemia." (PMID 36368937, 2022). "Improved quality of life 12 months after PTX especially in patients with higher hypercalcemia and a relative lipolytic activity of PTH could explain this finding." (PMID 35268464, 2022). "Despite this, hypercalcemia persisted with PTH suppression (1.8 pg/ml)." (PMID 35664896, 2022). "Patients with hypercalcemia may experience a life-threatening hypercalcemic crisis due to the high level of PTH secondary to a parathyroid carcinoma or a giant parathyroid adenoma." (PMID 35414046, 2022). "When patients become symptomatic, it is usually a combination of increased PTH and hypercalcemia." (PMID 36408083, 2022). "Mid-morning parathyroid hormone (PTH) level may be required to exclude endocrine related hypercalcaemia (usually low in malignancy-related hypercalcaemia)." (PMID 34648136, 2022). "At that time, a very low activity of ALP, hypercalcemia, and decreased PTH concentration was found." (PMID 35453912, 2022). "Therefore, cinacalcet can successfully reduce PTH concentrations and improve the serum calcium and phosphate control, and hypercalcemia can be corrected under such treatment." (PMID 36015101, 2022). "The most common manifestations are severe hypercalcemia and inappropriately elevated PTH." (PMID 36303876, 2022). "PTH-rp can also be measured and is highly specific for malignancy-related hypercalcaemia." (PMID 34648136, 2022). "Work-up for hypercalcemia revealed suppression of parathyroid hormone (PTH; 6 pg/dL; n: 18–80 pg/dL), normal PTH-related protein (PTH-RP; 20 pg/dL; n: 0–23 pg/dL); decreased 25-hydroxyvitamin D (9.2 ng/d; n: 30–100 ng/dL), 1,25-dihydroxyvitamin D total, D2, and D3 (< 8 pg/mL; n: 19.9–79.3 pg/dL)." (PMID 35815408, 2022). "Oversuppression of parathyroid hormone is a concern in patients with stage 3–4 CKD treated with calcitriol or active analogues because low parathyroid hormone concentration is associated with adynamic bone disease and hypercalcaemia." (PMID 34626363, 2022).